CD4 (CD4 molecule)
Diseases named in the same sentence as CD4 in open-access papers (continued):
Sharing a sentence is not in itself a finding about the gene and the disease.
Pneumocystis pneumonia (continued). "Though limited by a small sample size and a short observation duration, this study suggests that discontinuation of prophylaxis for pneumocystosis may be safe in selected patients who continue to receive HAART despite of low CD4 counts." (PMID 20492660, 2010). "(Previous studies from our laboratory have shown that CD4-depleted mice will ultimately die of Pneumocystis pneumonia if depletion of CD4+ lymphocytes is maintained for greater than 8 weeks; they will clear the infection when treatment with anti-CD4 is stopped)." (PMID 19558669, 2009). "Animal models of Pneumocystis pneumonia (PCP) have been used for the discovery of new antimicrobial agents and vaccine testing as well as understanding CD4+ T cell immunity in the lung." (PMID 33491669, 2021). "First, this is not a clinical trial to compare the risk for pneumocystosis between patients who discontinue primary or secondary prophylaxis when their CD4 counts remain < 200 cells/μL and those who discontinue prophylaxis when their CD4 counts increase to ≧200 cells/μL." (PMID 20492660, 2010). "Reduced CD4+, CD8+, and natural killer cells correlate with increased mortality in pneumocystis pneumonia among HIV-negative individuals." (PMID 41031357, 2025). "Pneumocystis jirovecii pneumonia (PJP) is a common opportunistic infection in people living with HIV (PLHIV), particularly when the cluster of differentiation 4+ (CD4+) T-cell count falls below 200 cells/mm3." (PMID 41141140, 2025). "It was reported that one-third of Pneumocystis pneumonia cases occur in HIV-negative immunocompromised patients, possibility of due to an increase in infection when the CD4+ lymphocyte counts drop below 200 cells/μl." (PMID 36237437, 2022). "CD4+ T cells and STAT4/6, at least in a mouse model of pneumocystis pneumonia, are necessary for M2 macrophage MMP12 expression and RELM-α and CCL17 production." (PMID 29304863, 2018). "In North America and Europe, TS prophylaxis prevents Pneumocystis jirovecii pneumonia (PCP) and toxoplasmosis, and is discontinued after the CD4 cell count reaches 200/mm3." (PMID 27431995, 2016). "The variables studied were age, sex, last CD4/CD8 count, CD4 nadir, herpes or pneumocystosis, cotrimoxazole and fluconazole use, antiretroviral treatment and the notion of recent initiation of HAART." (PMID 24498446, 2014). "Our algorithm follows WHO guidance and CD4 counts are helpful beyond defining eligibility of patients for AHD screening, e.g. to assess the probability of pneumocystis pneumonia in patients with shortness of breath or of toxoplasmosis with focal neurological symptoms." (PMID 35433287, 2022). "A 22-year-old male Chinese patient with diffuse exudative lesions in both lungs and initial symptoms of cough and dyspnoea was diagnosed with Pneumocystis jirovecii pneumonia (PJP) by aetiological examination, and the patient’s plasma CD4+ T-cell count was extremely low." (PMID 31200652, 2019). "Among the 139 patients who continued primary or secondary prophylaxis after CD4 counts increased to ≧200 cells/μL after HAART, 2 cases of pneumocystosis developed after a total observation duration of 444 PY, with an incidence rate of 0.45 per 100 PY (95% CI, 0.05, 1.63)." (PMID 20492660, 2010). "The incidence rate of pneumocystosis in 165 patients with baseline CD4 counts of <200 cells/μL who did not receive either primary or secondary prophylaxis for pneumocystosis was 2.88 per 100 PY (95% CI, 0.59 to 8.43)." (PMID 20492660, 2010). "In one study, primary or secondary prophylaxis was discontinued when CD4 count was <200 cells/μL in 98 patients who received HAART without occurrence of pneumocystosis." (PMID 20492660, 2010). "In the HAART era, the majority of cases of pneumocystosis occur in patients who are unaware of their HIV infection or have delay in seeking HIV care, or in those with advanced immunosuppression (CD4+ count < 100 cells/μL) who have limited access to HAART and related HIV care." (PMID 20492660, 2010).
Pneumocystis pneumonia (continued). "Of the potential host factors that could affect antibody responses, we were most interested in CD4+ cells, HIV RNA level, and previous history of pneumocystosis." (PMID 16965702, 2006). "However, in a murine model of pneumocystosis, neither the memory CD4+ T cells nor B cells are required for clearance of infection." (PMID 36177012, 2022). "Between April 1997 and September 2007, 660 patients fulfilled the inclusion criteria: 165 patients with baseline CD4 counts of <200 cells/μL did not receive primary prophylaxis for pneumocystosis; and 279 and 216 patients received primary and secondary prophylaxis, respectively." (PMID 20492660, 2010). "CD4+ cell count or differences in the treatment of pneumocystosis might also play a role in the ability of patients without a previous history of pneumocystosis to mount an antibody response, but our analysis was not powered to analyze multiple factors simultaneously." (PMID 16965702, 2006). "In mice without CD4 + T cell infected with P. murina showed gut microbial community that was significantly distinct from normal mice with P. murina infection, indicating that lacking of CD4 + T cells may alter the gut microbiota as well in Pneumocystis pneumonia." (PMID 32158441, 2020).
Thrombocytopenia (104 papers, 2006 to 2026). A reduction in the number of circulating thrombocytes. "Age, CD4 count (<200 cells/mm3-late presenters), and thrombocytopenia were identified as independent risk factors for mortality in the 58 patients (22%) who died after diagnosis." (PMID 40748951, 2025). "A 42-year-old man with a past medical history of uncontrolled HIV with a CD4 count of 15/mm3 and viral load (VL) of 2052 copies/mL presented to the hospital for severe thrombocytopenia with associated epistaxis and petechiae." (PMID 39247045, 2024). "We identified ASXL1 mutation and low CD45RA+CD4+ T-cell prevalence as potential aggravators of thrombocytopenia." (PMID 39574914, 2024). "The ACR criteria positively associated with CD4+ T cells cluster 1 were history of seizure and thrombocytopenia." (PMID 33883687, 2021). "The study found a significant association between thrombocytopenia and other cytopenias, CD4+ T cell counts, antiretroviral treatment(ART), and deteriorating HIV stage." (PMID 29760930, 2018). "Thrombocytopenia has been independently associated with chronic active hepatitis B virus infection, male gender, low absolute neutrophil count and low CD4 count." (PMID 25209550, 2014). "These antibodies were associated with pathologic consequences, such as thrombocytopenia, thrombosis and naïve cell depletion of both CD4+ and CD8+ T cells in blood and tissues." (PMID 19360097, 2009). "ASXL1 mutation and low CD45RA+CD4+ T-cell counts correlated with progression to thrombocytopenia." (PMID 39574914, 2024). "The physician should critically evaluate the associated factors such as age, CD4+ T level, and treatment modality which may enhance the risk of thrombocytopenia in HIV patients." (PMID 36412670, 2022). "However, there is a paucity of pooled prevalence data and associated haematological markers such as CD4+ T for thrombocytopenia in HIV patients, and pooled prevalence data may be helpful to develop health care policy and guidelines for preventive measures." (PMID 36412670, 2022). "Similarly thrombocytopenia increased with decreasing CD+4 T-cell count; being 6.5% - 22.5% within different CD+4 T-cell count categories and showed significant association with CD4 count <200 cells/mm3 [P = 0.02]." (PMID 30759131, 2019). "However, we showed that voluntary HIV testing prevented late and very late diagnoses of HIV infection and that nonspecific abnormal blood test results, such as hypergammaglobulinemia and thrombocytopenia, were significantly associated with low CD4 counts of < 200/mm3." (PMID 26934235, 2016). "The multivariable logistic regression analysis identified older age, low CD4 count (<200 cells/mm3), and thrombocytopenia as independent predictors of mortality." (PMID 40748951, 2025). "Our results implicate the involvement of an inflammatory process prior to thrombocytopenia progression and suggest that CD4+ T-cell status is a potential indicator of progression to thrombocytopenia." (PMID 39574914, 2024). "Many studies have found that the prevalence of thrombocytopenia decreases with higher CD4+ T-lymphocyte counts; the prevalence drops to 0 in patients with CD4+ T lymphocyte counts of > 350 cells/μL." (PMID 35264228, 2022). "Routine assessment for thrombocytopenia along with evaluation of CD4+ T level in subjects living with HIV should be performed to optimize clinical management." (PMID 36412670, 2022). "In bivariate analysis, thrombocytopenia was associated with age group, male gender, occupational status, marital status, WHO clinical stage III and IV, AZT based ART regimen, CD4 count less than 200 cell/mm3." (PMID 32931523, 2020). "As concerns CD4-count, rate of thrombocytopenia was 16.2% (42/259) in those with ≥ 200 CD4/mm3 versus 33.3% (17/51) with < 200 CD4/mm3 (p = 0.0003)." (PMID 31554515, 2019). "After adjusting for sex, ART, viral load and CD4, viral load and ART exposure were significantly associated with decreased risk of thrombocytopenia." (PMID 31554515, 2019).
Thrombocytopenia (continued). "After adjusting for sex, ART, viral load and CD4, Viral load and ART exposure were significantly associated with decreased risk of thrombocytopenia (p < 0.001)." (PMID 31554515, 2019). "After adjusting for sex, ART, viral load and CD4, Viral load and ART exposure were significantly associated with decreased risk of thrombocytopenia (p < 0.05)." (PMID 31554515, 2019). "According to the present study, the prevalence of thrombocytopenia was increased with decreasing CD4 count both before and after HARRT initiation." (PMID 29760930, 2018). "HIV patients whose CD4 counts < 200 Cells/μl were more likely to have thrombocytopenia than HIV patients whose CD4 count ≥350 Cells/μl." (PMID 29760930, 2018). "Thrombocytopenia was more prevalent among HIV positive patients who had a CD4 + T cell count of < 200 cells/μl." (PMID 29760930, 2018). "Thrombocytopenia patients and chronic lymphocytic leukemia patients had a higher level (in both percentage and absolute number) of CD4+/PD1+ lymphocytes than of healthy controls." (PMID 30069490, 2018). "HIV patients with old age (age greater than 50 years), lower CD4 + T cell count and AZT based HAART regimen had an increased risk of developing thrombocytopenia." (PMID 29760930, 2018). "HIV patients whose CD4 counts less than 200 cells /mm3 were 4.4 times more likely to have thrombocytopenia than HIV patients whose CD4 counts greater than or equals to 350cells/mm3." (PMID 29760930, 2018). "In the current study, 7 patients underwent HIV testing during the differential diagnosis of thrombocytopenia, including 2 patients with pancytopenia; the CD4 counts in 4 of these 7 patients (57.1%) was <200 cells/mm3 at the time of diagnosing HIV infection." (PMID 26934235, 2016). "CD4 cell counts were significantly higher in the HAART eras at the time of thrombocytopenia (p < 0.001)." (PMID 26498280, 2015). "HIV patients whose age ≥ 50 years old were 2.5 times more likely to have thrombocytopenia and those patients whose CD4 count < 350 were 2.6 times more likely to have thrombocytopenia than HIV patients whose CD4 count ≥500." (PMID 24387326, 2014). "Thrombocytopenia was associated with sex, HAART status at the time of enrolment and CD4 count category 50 to < 200 cells/μl." (PMID 25209550, 2014). "For example, the prevalence of thrombocytopenia was proportionally high among patients who had a CD4 lymphocyte count of ≤ 350 cells/μL and low among patients with a CD4 count > 500 cells/μL." (PMID 24387326, 2014). "Regarding thrombocytopenia, the model included the type of pegIFNα prescribed, stratified CD4 cell count, and SOCS3 rs4969170 genotype." (PMID 23133602, 2012). "The reasons to started ART were worsening of clinical criteria in 3 children (1 Pneumocystis jiroveci pneumonia and 2 severe thrombocytopenia) and immunologic criteria in 66 children (63 for CD4 <15% and 3 for CD4 <20%)." (PMID 23181827, 2012). "- Increased prevalence of thrombocytopenia observed in PLWHA with CD4 count <200 cells/μL." (PMID 32623456, 2021). "With sustained plasma viral loads of 105 to 106 RNA copies/ml for the past 15 years, this chimpanzee developed CD4+ T cell depletion (220 cells/μl), thrombocytopenia (90,000 platelets/μl), and persistent soft tissue infections refractory to antibacterial therapy." (PMID 28576126, 2017). "In contrast to thrombocytopenia more commonly present in persons with late stage HIV disease prior to the HAART era, the majority of cases in the later HAART era were associated with CD4 cell counts >350 cells/μl." (PMID 26498280, 2015). "Similarly out of 97 subjects with leucopenia, 82% (n = 80) had CD4 < 200 and of the 33 subjects with thrombocytopenia, 75% (n = 25) had CD4 count <200." (PMID 25209550, 2014). "Thrombocytopenia, however, increases as CD4 decreases (p = 0.007)." (PMID 24666771, 2014). "Thrombocytopenia is correlated with low CD4 cell count and older age." (PMID 19678930, 2009).
Thrombocytopenia (continued). "Notably, in the present study, two of the three patients with severe thrombocytopenia had a CD4 count above 200 cells/μl." (PMID 16916475, 2006). "Although we could not clarify the prevalence of hypergammaglobulinemia and thrombocytopenia in all patients, these results indicate that abnormal blood test results were significantly associated with low CD4 counts." (PMID 26934235, 2016). "Baseline platelet count, high CD4/CD8 CAR-T cell ratio, and high baseline IL-2 levels significantly influence long-term thrombocytopenia levels." (PMID 39253080, 2024). "On admission, the patient had malignant hypertension, microangiopathic hemolytic anemia, thrombocytopenia, and acute renal failure, along with high HIV viral loads and low CD4 counts." (PMID 39130838, 2024). "More than 10 studies reported the same outcomes, including ORR, DCR, KPS, thrombocytopenia, liver/renaldysfunction, neurotoxicity, nausea/vomiting, diarrhea, leukopenia, CD3+ T cells, CD4+ T cells, CD8+ T cells, CD4+/CD8+ T cells ratio, and CEA." (PMID 35650714, 2023). "The difference between the male and female patients in the laboratory test results is mainly manifested in the count of lymphocytes and T lymphocytes (CD3 / CD4 / CD8) and thrombocytopenia." (PMID 34551393, 2021). "The aim of our study was to assess the burden of thrombocytopenia according to antiretroviral therapy (ART), viremia and CD4-lymphocytes count of PLHIV." (PMID 31554515, 2019). "The circulating CD4+CD161+ T cell levels were positively correlated with ESR, thrombocytopenia, and anti-SSB in pSS." (PMID 26436101, 2015). "More than half of our subjects with thrombocytopenia after 1996 were HAART-naïve, consistent with HAART initiation guidelines at the time based on their CD4 cell levels." (PMID 26498280, 2015). "In conclusion, as CD4 counts of HIV patients decreasing, they have more likely to have thrombocytopenia." (PMID 24387326, 2014). "However, CD4 count was not statistically associated with prevalence of thrombocytopenia (P > 0.05)." (PMID 24387326, 2014). "We therefore assessed the prevalence of thrombocytopenia in HIV-infected HAART naive patients and also tried to determine the relationship between thrombocytopenia and CD4 cell counts in these patients." (PMID 24387326, 2014). "During follow up, one patient developed an acute retroviral syndrome and two patients presented thrombocytopenia (< 50,000 platelet/mm3) for which they had to restart HAART (with CD4+ > 350 cell/μL)." (PMID 18302775, 2008). "The protection by molnupiravir was associated with lower virus burden in mouse tissues, improvement of T-cell (CD4+, CD8+) and B-cell (follicular) profiles in the spleen, improvement of severe thrombocytopenia, and reduced pathology in the spleen and liver of BRBV-infected mice." (PMID 40910687, 2025). "In this case, the patient had a critically low CD4 count (21 cells/mm3) and persistent viral replication, indicating severe immunosuppression and emphasizing HIV’s role in thrombocytopenia through both direct and indirect effects on the bone marrow and immune system." (PMID 40755707, 2025). "Multivariable analysis confirmed older age (OR: 1.05, 95% CI: 1.02, 1.09), thrombocytopenia (OR: 2.54, 95% CI: 1.10,5.90), and low CD4 count, especially with non-homosexual transmission routes (OR: 15.6, 95% CI: 1.85,186), as independent mortality predictors." (PMID 40748951, 2025). "We hypothesize that cases of thrombocytopenia in HIV patients may be multifactorial, but different studies have different findings, for example, level of CD4+ T, age, and gender-specific vulnerability." (PMID 36412670, 2022). "Our results suggest that thrombocytopenia in HIV patients is multifactorial and age, level of CD4+ T, and treatment modality may be considered as important cofactors." (PMID 36412670, 2022). "The low prevalence of thrombocytopenia among HAART users might be due to the role of HAART in reducing the viral load and improving CD4 T cell count." (PMID 34543340, 2021).